IFNA21 (interferon alpha 21)
Description:
Produced by macrophages, IFN-alpha have antiviral activities. Interferon stimulates the production of two enzymes: a protein kinase and an oligoadenylate synthetase.
Synonyms: LeIF F; IFN-alphaI; leIF-F
Tractability: Antibody: a drug acting on it is in phase 2 or 3 trials; its Gene Ontology location is reachable by antibodies, with high confidence; UniProt places it where antibodies can reach, with medium confidence; UniProt predicts a signal peptide or a membrane-spanning region.
Gene: Protein-coding gene on chromosome 9 (21,165,637 to 21,166,660, reverse strand). Ensembl gene ENSG00000137080.
Subcellular location: Secreted
Pathways (Reactome):
Immune System: Interferon alpha/beta signaling; Regulation of IFNA/IFNB signaling; TRAF6 mediated IRF7 activation
Disease: Evasion by RSV of host interferon responses; SARS-CoV-2 activates/modulates innate and adaptive immune responses
Hemostasis: Factors involved in megakaryocyte development and platelet production
Gene Ontology:
Molecular function: protein binding; cytokine activity; cytokine receptor binding; type I interferon receptor binding
Biological process: adaptive immune response; B cell activation involved in immune response; cellular response to virus; humoral immune response; natural killer cell activation involved in immune response; response to exogenous dsRNA; T cell activation involved in immune response; type I interferon-mediated signaling pathway; defense response
Cellular component: extracellular region
Genetic constraint (gnomAD): Loss-of-function variants: 1 observed, 0.45 expected, observed/expected ratio (o/e) 2.24. That is too few expected variants to judge how well the gene tolerates losing a copy. Missense variants: 272 observed, 215.56 expected, observed/expected ratio (o/e) 1.26, 90% interval 1.14 to 1.39. Synonymous variants: 101 observed, 84.01 expected, observed/expected ratio (o/e) 1.2, 90% interval 1.02 to 1.42.
Homologues: Orthologues: chimpanzee IFNA21 (100% identical), macaque IFNA10 (89% identical), macaque IFNA21 (89% identical), pig IFN-ALPHA-9 (68% identical), pig IFN-ALPHA-15 (68% identical), pig IFN-ALPHA-13 (67% identical), pig IFN-ALPHA-8 (67% identical), pig IFNA1 (67% identical), pig IFN-ALPHA-4 (65% identical), rabbit IF1AD2 (65% identical), pig IFN-ALPHA-17 (63% identical), rabbit IF1AD7 (63% identical), and 33 more. Paralogues in human: IFNA4 (92% identical), IFNA10 (91% identical), IFNA17 (91% identical), IFNA7 (88% identical), IFNA5 (87% identical), IFNA16 (86% identical), IFNA14 (82% identical), IFNA13 (81% identical), IFNA2 (81% identical), IFNA6 (81% identical), IFNA8 (81% identical), IFNA1 (81% identical), and 4 more.
Diseases named in the same sentence as IFNA21 in open-access papers:
IFNA21 is named in the same sentence as 15 diseases in open-access papers, as found by Europe PMC text mining. Sharing a sentence is not in itself a finding about the gene and the disease. The quoted sentences say what the papers report.
viral infection (2 papers, 2017 to 2021). "IFNA21 encodes type I interferon and is mainly involved in innate immune response against viral infection." (PMID 28928442, 2017). "IFNA21 is one of the genes correlated with BAVT and is a member of the alpha interferon gene cluster that are produced in response to viral infection." (PMID 33807612, 2021).
Acquired Immunodeficiency Syndrome (1 paper, 2024). "Additionally, patients with Acquired Immunodeficiency Syndrome (AIDS; stage C) showed significantly higher expression of IFNA1/13, IFNA8, IFNA14, IFNA16, IFNA17, and IFNA21 mRNA." (PMID 38543729, 2024).
Cirrhosis (1 paper, 2012). A chronic disorder of the liver in which liver tissue becomes scarred and is partially replaced by regenerative nodules and fibrotic tissue resulting in loss of liver function. "ATG16L2, DEFB114, FAM14B, IFNA21, IL8RB and KIR2DL genes were up-regulated in cirrhosis, whereas, FCRL3, IFITM2 and OAS2 genes were up-regulated in initial fibrosis." (PMID 22397681, 2012).
melanoma (1 paper, 2012). A malignant, usually aggressive tumor composed of atypical, neoplastic melanocytes. "Based on our observations, we hypothesize that the region of 26 kb encompassing IFNW1 and IFNA21 could be a regulatory region in chromosome 9p22, containing natural genetic variants, which might play a role in disease outcome in melanoma." (PMID 23209811, 2012).
tumor (2 papers, 2016 to 2018). "In line with this, we found in the TCGA dataset that loss of expression of IFNA13, IFNA21, IFNA6, IFNA8, IFNB1, or IFNW1 was correlated to poor survival, increasing the evidence for the importance of the tumor-stroma microenvironment interaction in gliomagenesis." (PMID 27172220, 2016).
IFNA21 also shares sentences with these, for which no sentence is quoted: COVID-19 (2 papers); coronary artery disease (1); herpes zoster (1); infection (1); Kawasaki disease (1); lupus (1); lupus nephritis (1); otitis media (1); rubella (1); T-cell acute lymphoblastic leukemia (1).